EPS15L1 (epidermal growth factor receptor pathway substrate 15 like 1)
Description:
Seems to be a constitutive component of clathrin-coated pits that is required for receptor-mediated endocytosis. Involved in endocytosis of integrin beta-1 (ITGB1) and transferrin receptor (TFR); internalization of ITGB1 as DAB2-dependent cargo but not TFR seems to require association with DAB2.
Synonyms: Eps15R
Tractability: Antibody: its Gene Ontology location is reachable by antibodies, with high confidence; UniProt places it where antibodies can reach, with medium confidence. PROTAC: ubiquitination databases record sites on it; its protein half-life has been measured.
Gene: Protein-coding gene on chromosome 19 (16,355,225 to 16,472,085, reverse strand). Ensembl gene ENSG00000127527.
Subcellular location: Cell membrane; Nucleus; Membrane, coated pit
Subcellular location (Human Protein Atlas): Vesicles
Pathways (Reactome):
Vesicle-mediated transport: Cargo recognition for clathrin-mediated endocytosis; Clathrin-mediated endocytosis
Signal Transduction: EGFR downregulation
Gene Ontology:
Molecular function: cadherin binding; protein binding; protein-macromolecule adaptor activity; calcium ion binding
Biological process: synaptic vesicle endocytosis
Cellular component: membrane; clathrin coat of coated pit; cytosol; plasma membrane; cytoplasm; nucleus; presynapse
Genetic constraint (gnomAD): Loss-of-function variants: 39 observed, 112.47 expected, observed/expected ratio (o/e) 0.35, 90% interval 0.27 to 0.45. The upper end of that interval is the gene's LOEUF score, 0.45, which puts it in group 2 of 6, group 1 being the genes least tolerant of losing a copy. Missense variants: 917 observed, 1,155.6 expected, observed/expected ratio (o/e) 0.79, 90% interval 0.75 to 0.84. Synonymous variants: 428 observed, 467.03 expected, observed/expected ratio (o/e) 0.92, 90% interval 0.85 to 0.99.
Homologues: Orthologues: chimpanzee EPS15L1 (99% identical), pig EPS15L1 (96% identical), dog EPS15L1 (96% identical), rat Eps15l1 (93% identical), mouse Eps15l1 (93% identical), guinea pig EPS15L1 (88% identical), macaque EPS15L1 (86% identical), rabbit EPS15L1 (85% identical), tropical clawed frog eps15l1 (75% identical), zebrafish eps15l1a (72% identical). Paralogues in human: EPS15 (48% identical), ITSN1 (23% identical), ITSN2 (23% identical), REPS1 (16% identical), REPS2 (14% identical), EHD1 (11% identical), EHD3 (11% identical), EHD2 (10% identical), EHD4 (10% identical), SRL (7% identical).
Diseases named in the same sentence as EPS15L1 in open-access papers:
EPS15L1 is named in the same sentence as 10 diseases in open-access papers, as found by Europe PMC text mining. Sharing a sentence is not in itself a finding about the gene and the disease. The quoted sentences say what the papers report.
mastitis (2 papers, 2018 to 2023). Inflammation of breast tissue during lactation or postpartum due to an obstructed duct or infection. "For recoverability from mastitis we suggest EPS15L1 (essential for lymphocyte development), PDGFD (involves in macrophage recruitment and wound healing), and PTX3 (involved in regulating inflammation) as candidates for the causal genes." (PMID 29755506, 2018). "Similarly, the SNP rs29012637 on BTA7, an intergenic variant, was significantly associated with recoverability from mastitis, and is mapped very near to the gene EPS15L1 (epidermal growth factor receptor pathway substrate 15 like 1)." (PMID 29755506, 2018). "Therefore, the gene EPS15L1 could be considered as a potential candidate gene for recoverability from mastitis because it plays an important role in promoting production of lymphocytes, which are main components in the immune system." (PMID 29755506, 2018).
anemia (1 paper, 2020). A reduction in the number of red blood cells, the amount of hemoglobin, and/or the volume of packed red blood cells. "Iron deficiency-induced anemia is present in hematopoietic-specific conditional Eps15/Eps15L1-double-KO mice." (PMID 32943616, 2020).
hepatocellular carcinoma (1 paper, 2023). A malignant tumor that arises from hepatocytes. "Next, a literature search was conducted to focus on proteins specifically associated with liver disease in general, which selected 20 proteins, seven of which (i.e., CEP55, CLIC1, EPS15L1, G6PD, KIF11, SLC1A5, and TK1) were found to be specifically associated with hepatocellular carcinoma." (PMID 37627157, 2023).
tumor (5 papers, 2019 to 2025). "Specifically, Kruppel-like factor 2 (KLF2), associated gene of lnc-EPS15L1-2:1 from Cis and Trans analyses, was reported as a terminal component of tumor proliferation and metastasis related pathway axis." (PMID 31355249, 2019). "pQTL results may more closely reflect functional mechanisms (such as EPS15L1 protein directly participating in tumor pathways), while eQTLs may reflect indirect effects of transcriptional regulation." (PMID 41216288, 2025). "Moreover, emerging research indicates a potential correlation between the fusion of mRNA-lncRNA, leading to the production of the chimeric protein EPS15L1-lncOR7C2-1, which facilitates tumour growth by potentially controlling GSDME-related pyroptosis." (PMID 39267831, 2024). "Immunohistochemistry results showed that EPS15L1 and HGS were strongly expressed in tumor tissues and slightly expressed in normal tissues, and semi-quantitative analysis showed significant difference." (PMID 41216288, 2025). "The gene EPS15L1, an acknowledged target of miR-4644 and miR-1233-3p in PLR, may regulate immune cell development and pathways involved in anti-tumor immunity." (PMID 37950349, 2024).
cancer (3 papers, 2012 to 2025). A tumor composed of atypical neoplastic, often pleomorphic cells that invade other tissues. "KDM4B-G039927 and EPS15L1-lncOR7C2–1 Fusions: In a systematic study of the lncRNA fusion landscape across cancer types using available cancer RNA databases, fusions with lncRNAs were found to be correlated with DNA damage and cancer stemness." (PMID 38919532, 2024).
EPS15L1 also shares sentences with these, for which no sentence is quoted: depression (1 paper); liver cancer (1); liver disease (1); mental retardation (1); pertussis (1).